ADAMTS13 (ADAM metallopeptidase with thrombospondin type 1 motif 13)
Diseases named in the same sentence as ADAMTS13 in open-access papers (continued):
Sharing a sentence is not in itself a finding about the gene and the disease.
tumor (17 papers, 2012 to 2025). "In an avian xenograft tumor model, ADAMTS13 loss led to increased vascularization, decreased vascular length, and diminished tumor growth, accompanied by reduced expression of multiple key angiogenic and angioplastic factors." (PMID 41211185, 2025). "Increased ADAMTS-13 activity is associated with increased serum lactate, an important plasma molecule in lactate metabolism that has been implicated in tumor progression, metastasis and micro thrombosis." (PMID 37691826, 2023). "They further showed that the combination of VWF release and decreased local ADAMTS‐13 in the tumor tissue is likely to cause a procoagulatory milieu." (PMID 31294335, 2019). "Understanding the relationship between VWF and ADAMTS13 in HCC could provide valuable insights into the mechanisms underlying tumor development and progression." (PMID 40699668, 2025). "In conclusion, we identified an aberrant expression and alternative function of ADAMTS13 in PDAC linked to tumor progression, plasticity, and angiogenesis, partly induced by the peripancreatic fat tissue, making this metalloproteinase an interesting target for personalized therapies." (PMID 41211185, 2025). "To examine the effects of adipokines, particularly leptin, on ADAMTS13 regulation during tumor development, we employed the chorioallantoic membrane (CAM) xenograft model." (PMID 41211185, 2025). "We show multifaceted effects of ADAMTS13: on the one hand, there is a tumor‐promoting role by facilitating migration and invasion, induction of mesenchymal markers and matrix metalloproteinases, and tumor growth." (PMID 41211185, 2025). "ADAMTS13 has been recognized as a tumor-suppressive circular RNA that functions as a sponge for miR-484, though its specific target gene remains unidentified." (PMID 40699668, 2025). "Using a proteome profiler array, we identified the adipokine leptin as an inducer of ADAMTS13 in tumor cells." (PMID 41211185, 2025). "The expression of the three genes, COQ2, MPC1, and ADAMTS13, in normal and tumor tissues was analyzed, revealing that the expression of MPC1 was higher in normal tissues, while ADAMTS13 was higher in tumor tissues." (PMID 37691826, 2023). "It was observed that the expression level of MPC1 was clearly elevated in adjacent normal tissues comparing with CRC, while ADAMTS13 was considerably upregulated in tumor tissues in contrast to normal tissues." (PMID 37691826, 2023). "VWF and ADAMTS13 have been explored as tumor biomarkers for the detection and prognostication of certain malignancies; however, the results are underdeveloped and so currently not utilized for clinical use." (PMID 35327035, 2022). "It is likely that VWF and ADAMTS13 promote tumor metastasis via interactions and effects on endothelial cells, platelets and the tumor microenvironment." (PMID 35327035, 2022). "We examined the relationship between the VWF:Ag/ADAMTS13:AC ratio and serum tumor markers, such as AFP, DCP, and AFP-L3%." (PMID 31638892, 2019). "The von Willebrand factor: Ag/ADAMTS13:AC ratio was exclusively correlated with tumor volume and stage as well as serum vascular endothelial growth factor levels." (PMID 31638892, 2019). "Altogether, local pro‐ and anti‐tumor effects and systemic effects may be outweighed by another, thus rendering a slightly better prognosis for patients with higher ADAMTS13 expression." (PMID 41211185, 2025). "In particular, tumor cells located in the tumor periphery showed strong vimentin positivity in controls, whereas ADAMTS13‐deficient tumors showed almost no vimentin staining." (PMID 41211185, 2025). "In addition to MMP9, we identified several factors regulated by ADAMTS13 that play a decisive role in the formation of blood vessels and can therefore significantly influence tumor growth." (PMID 41211185, 2025). "Moreover, ADAMTS13 exhibited close correlations with multiple pathways related to tumor occurrence, tumor cell proliferation, and migration." (PMID 37691826, 2023).
tumor (continued). "Reduced ADAMTS13 levels may, therefore, increase the chance of tumor metastasis by increasing the availability of large VWF multimers." (PMID 35327035, 2022). "In step with VWF having a role in tumor metastasis, ADAMTS13 may also have a supportive role to play here." (PMID 35327035, 2022). "Using paired HCC samples from TCGA database, we observed a very significant decrease of ADAMTS13 expression in tumor compared to adjacent non tumor tissues (3.8 × 10−21), however ADAMTS13 expression was not predictive for prognosis in the whole unpaired cohort." (PMID 33805340, 2021). "In our lymphatic tumor model, neither VWF deficiency nor ADAMTS13 deficiency had a significant effect on primary tumor development and metastasis formation." (PMID 27602496, 2016). "Factors such as impaired liver function, chronic liver inflammation, fibrosis, cirrhosis, increased systemic inflammation, tumor-associated cytokines (e.g., IL-6, TNF-α), tumor hypoxia, and elevated VWF levels in HCC may also contribute to a relative deficiency of ADAMTS13." (PMID 40699668, 2025). "Moreover, intrapancreatic adipocytes may serve as an additional source of adipokines, contributing to the variable ADAMTS13 distribution at both the invasive front and tumor center." (PMID 41211185, 2025). "At the same time, low levels of ADAMTS13 may enhance the pro-tumor effects of VWF." (PMID 40699668, 2025). "The mechanisms driving ADAMTS13 induction in tumor cells remain unclear." (PMID 41211185, 2025). "Additionally, cytokines, inflammatory signals, or hypoxia within the tumor microenvironment may regulate ADAMTS13 levels independently of methylation status." (PMID 40699668, 2025). "Also, a novel spliced ADAMTS13 transcript was found in both hepatic stellate cells and HCC cell lines suggesting that tumor cells could also participate in expression of ADAMTS13 in HCC." (PMID 33805340, 2021). "Notably, ADAMTS13 deficiency resulted in a prolonged lifetime for VWF fibers associated with higher vessel density and size, thus supporting a role of EC activation and luminal VWF networks in tumor angiogenesis." (PMID 27602496, 2016). "This suggests that ADAMTS13 might be involved in suppressing tumor cell invasion." (PMID 24213506, 2012). "ADAMTS13 (p = 0.002), SERPINA12 (p = 0.0186), and MMP12 (p = 0.0049) showed significantly increased expression at the mRNA level in the majority of tumor tissues compared to non‐neoplastic tissue." (PMID 41211185, 2025). "Accordingly, ADAMTS13 and MMP12 demonstrate robust expression at both the mRNA and protein levels in tumor tissue when compared to matching non‐neoplastic tissue." (PMID 41211185, 2025). "Consistent with the mRNA expression data, analysis of the same samples at the protein level also showed elevated expression of ADAMTS13 and, to a lesser extent, MMP12 in tumor tissue." (PMID 41211185, 2025). "ADAMTS13 and MMP9 were co‐expressed in both precursor lesions and invasive tumor cells, with MMP9 showing a largely uniform expression pattern." (PMID 41211185, 2025). "However, ADAMTS13's role in tumor progression remains largely unknown." (PMID 41211185, 2025). "Low ADAMTS-13 activity could result in elevated levels of highly polymeric von Willebrand factor (vWF), which might facilitate adhesive interactions with both circulating tumor cells and platelets, resulting in thrombus formation and the presumptive development of a metastatic colony." (PMID 36474619, 2022). "By contrast, expression of each of ADAMTS1, ADAM19, ADAMTS13, and ADAMTS17 in tumor tissue was 0.75-fold lower than that in NCL." (PMID 36230656, 2022). "It is thought that the accumulation of UL-VWF and downregulated ADAMTS13 levels lead to VWF-platelet aggregates and fibrin deposition in the tumor vasculature resulting in a prothrombotic milieu in certain disseminated malignancies." (PMID 35327035, 2022). "CircADAMTS13, derived from Exon 13–14 of the ADAMTS13 gene, was significantly downregulated in HCC tumor tissues." (PMID 30537115, 2019).
tumor (continued). "We determined the relationship of tumor volume and stage with the VWF:Ag/ADAMTS13:AC ratio and AFP-L3%." (PMID 31638892, 2019). "To evaluate the role of VWF fibers on primary tumor growth, we analyzed tumor growth in wild type (WT) mice, VWF−/− and ADAMTS13−/− mice." (PMID 27602496, 2016). "Modulating VWF expression may enhance tumor suppression, and addressing the imbalance between VWF and ADAMTS13 may reduce angiogenesis and metastasis." (PMID 40699668, 2025). "Intradermal tumor cell inoculation in VWF- and ADAMTS13-deficient mice did not alter lymph node metastases compared with wild type animals." (PMID 27602496, 2016). "On the other hand, TMA associated with drugs, neoplasia, or infections has the same features as classic TTP but other mechanisms lead to thrombosis without ADAMTS13 inhibition." (PMID 27266265, 2016). "An uninvestigated factor in our study might be the systemic influence of ADAMTS13 in tumor patients, for example, potential negative effects of (micro)thromboembolism in distant organs (lung, heart, brain)." (PMID 41211185, 2025). "The upregulated proteins, including MMP9 (matrix metalloproteinase-9), ADAMTS13 (ADAM metallopeptidase with thrombospondin type 1 motif 13) and CRP (C-Reactive Protein), are known to be involved in extracellular matrix remodeling, vascular permeability and tumor-promoting inflammation." (PMID 36831450, 2023). "Therefore, whilst helpful in promoting the VWF–tumor–platelet-taxi, it is likely that low ADAMTS13 levels per se are not the sole driver of this phenomenon." (PMID 35327035, 2022). "Tumor volume and stage significantly correlated with the VWF:Ag/ADAMTS13:AC ratio (p = 0.0002 and p = 0.046, respectively) but not with the AFP-L3%." (PMID 31638892, 2019). "Perhaps tumor directed therapy, rather than systemic therapy, such that VWF/ADAMTS13 is only altered in the tumor microenvironment, may assist with mitigating this risk." (PMID 35327035, 2022). "Strikingly, immunohistochemical double staining of ADAMTS13 and vimentin in human PDAC tissues revealed co‐expression of ADAMTS13 and vimentin in tumor cell clusters with an invasive solid, trabecular growth pattern, while vimentin was absent in glandular tumor structures and precursor lesions." (PMID 41211185, 2025).
blood disorder (11 papers, 2005 to 2025). "Heterozygous P/LP variants in genes associated with other hematopoietic diseases or developmental disorders with autosomal recessive inheritance were identified in ADAMTS13, GBA1 (n=3), and VPS13B." (PMID 40766138, 2025). "Immune-mediated thrombotic thrombocytopenic purpura is a rare and challenging hematological disease caused by the antibody anti-ADAMTS13." (PMID 34884404, 2021). "Caplacizumab, with a cosine similarity score of 0.294, is approved for treating adult acquired thrombotic thrombocytopenic purpura (aTTP), a rare blood disorder caused by an autoantibody-mediated severe deficit in the von Willebrand factor (vWF) cleaving metalloproteinase ADAMTS13." (PMID 39264975, 2024). "To test this hypothesis, we investigated the influence of the ADAMTS13 rs2285489 SNP on transplant outcomes in a cohort of patients undergoing unrelated HLA-matched bone marrow transplantation (BMT) for hematologic malignancies through the Japan Marrow Donor Program (JMDP)." (PMID 30626079, 2019). "We retrospectively examined whether ADAMTS13 rs2285489 affected the transplant outcomes in a cohort of 281 patients who underwent unrelated human leukocyte antigen (HLA)-matched bone marrow transplantation for hematologic malignancies." (PMID 30626079, 2019).
bacterial infection (5 papers, 2019 to 2025). "We aimed to investigate the possible use of ADAMTS-13 as a prognostic marker in children with serious bacterial infection (SBI)." (PMID 31434239, 2019). "These observed associations of iTTP with bacterial infections have not yet been substantiated by any direct link to specific pathogen antigens resembling ADAMTS13." (PMID 40821327, 2025). "Additionally, due to our inclusion criteria, the registry included patients with very heterogeneous backgrounds, ranging from confirmed complement-mediated TMAs to various secondary TMAs not driven by bacterial infection or ADAMTS13 deficiency." (PMID 41102576, 2025).
cardiac disease (4 papers, 2021 to 2025). "In this review, we aim to describe the associations of VWF, ADAMTS13, and cardiac disease in some detail." (PMID 34564132, 2021). "We recommend that workers in the field of cardiac disease take a greater interest in both VWF and ADAMTS13, to both identify the opposing risks of bleeding and thrombosis, and to potentially consider supportive therapies or curative approaches, as the case may require." (PMID 34564132, 2021).
connective tissue disease (4 papers, 2011 to 2020). "In acquired TTP, antibodies toward ADAMTS13 may develop idiopathically or in association with another autoimmune condition or connective tissue disease." (PMID 30223886, 2018). "In addition, systemic connective tissue diseases are other conditions that can be associated with low but detectable levels of ADAMTS-13." (PMID 22206706, 2011).
genetic disorder (4 papers, 2020 to 2024). "This enzyme is a critical regulator of VWF function, and another example of starting at the bedside in patients with this puzzling rare genetic disorder, with the genetics then leading us to the ADAMTS13 gene and new insight into the molecular mechanisms underlying TTP." (PMID 39545422, 2024). "Despite an ultra-rare prevalence of pathogenic germline ADAMTS mutations responsible for genetic diseases (with the exception of ADAMTS13), it is important to accurately assess variants for their pathogenicity, together with metalloproteinase-specific functional assays for ADAMTS family proteins." (PMID 32183147, 2020). "We have chosen congenital TTP as a simple genetic disorder causing massively increased thrombotic risk and morbidity, but this approach could potentially be extended to the study of immuno‐mediated TTP, as it acts by circumventing the lack of ADAMTS‐13 functionality." (PMID 34934893, 2021).
infectious disease (3 papers, 2021 to 2024). A disorder directly resulting from the presence and activity of a microbial, viral, or parasitic agent in humans. "DIC patients with infectious disease showed significantly lower ADAMTS13 activity (30.0, 15.9-49.4%) than non-DIC patients with infectious disease (50.7, 36.3-68.8)." (PMID 39039520, 2024). "Low complement C3, normal ADAMTS13, and negative rheumatology and infectious disease panels suggested aHUS." (PMID 34912617, 2021).
vascular disorder (2 papers, 2021 to 2023). A general term used to describe any disease affecting blood vessels]. "A connection here (darkened) to this WVF/ADAMTS13 axis is reported for NOTCH1 which has roles in vascular epithelium, vascular disorders, and BBB function." (PMID 33946285, 2021).
brain) disease (1 paper, 2018). "In exploratory analyses, we found associations of ADAMTS13 activity with levels of VEGF, MMP-3, Tenascin-C, and TIMP-1, which might indeed indicate involvement in vascular remodelling, and in any case encourage further study of ADAMTS13 in relation to vascular (brain) disease and neurodegeneration." (PMID 29615758, 2018).
inflammation (1 paper, 2022). Aberrant reaction of the microcirculation characterized by movement of fluid and leukocytes from the blood into extravascular tissues. "Interestingly, von Willebrand Factor and its regulator ADAMTS-13 have been implicated in vascular inflammation and the development of immunothrombosis, providing a potential causative link between inflammation and coagulation in SARS-CoV-2 patients." (PMID 35482749, 2022).
neurodegenerative disease (1 paper, 2015). A disorder of the central nervous system characterized by gradual and progressive loss of neural tissue and neurologic function. "The results also clearly indicate that the interaction of ADAMTS-13 and NO may play an important role in the regulation and protection of the CNS microenvironment in neurodegenerative diseases." (PMID 25799514, 2015).
respiratory diseases (1 paper, 2023). "However, it is important to note that the plasma ADAMTS13 levels in these two studies were not compared to patients with PH associated with respiratory diseases." (PMID 37936223, 2023).
ADAMTS13 also shares sentences with these, for which no sentence is quoted: acute myocardial infarction (5 papers); vitamin B12 deficiency (5); Bacteremia (4); hemolysis (4); portal hypertension (4); systemic inflammatory response syndrome (4); thrombophilia (4); hepatorenal syndrome (3); acute-on-chronic liver failure (2); Alzheimer disease (2); brucellosis (2); complement 3 glomerulopathy (2); Encephalopathy (2); falciparum malaria (2); Graves disease (2); osteoarthritis (2); purpura (2); transient ischemic attack (2); acute chest syndrome (1); acute intermittent porphyria (1); acute respiratory distress syndrome (1); anticoagulant (1); arterial disease (1); Arthritis (1); autoimmune hemolytic anemia (1); autoimmune hepatitis (1); autosomal recessive disease (1); Behçet’s Disease (1); cardiac arrest (1); cardiomyopathies (1).
A further 78 diseases each share a sentence with ADAMTS13 in 1 paper.